SOD2 (superoxide dismutase 2)
Diseases named in the same sentence as SOD2 in open-access papers (continued):
Sharing a sentence is not in itself a finding about the gene and the disease.
tumor (continued). "The results show an increase in the levels of SOD2 to the conditioned medium of tumor cells sensitive to chemotherapy treatment." (PMID 36010852, 2022). "We have demonstrated that the extreme proteolytic stability shown by SOD2 in tumor cells is due to its quaternary structure." (PMID 36010852, 2022). "As a matter of fact, elevated content of SOD2 is correlated with increased tumor cell invasion, metastasis, proliferation, and resistance to apoptosis." (PMID 35164076, 2022). "A remarkable finding in this work is that there is a correlation relationship between SOD2 plasma levels and tumor volume in a group of BC patients (TNBC and Luminal B HER2-negative) during neoadjuvant treatment." (PMID 36010852, 2022). "Different theories have been proposed about the function of the SOD2 enzyme in the regulation of oxidative stress that ROS generates (tumor promoter) in the cell, and the development of cancer." (PMID 36354667, 2022). "While reduced SOD2 expression is commonly reported in the early stages of tumor growth, some studies report elevated levels of SOD2 during metastatic progression." (PMID 35164076, 2022). "The reduction in tumor size in patients undergoing neoadjuvant therapy correlates with the changes in the circulating levels of SOD2, despite their different SOD2 baseline levels." (PMID 36010852, 2022). "Overexpression of SOD2 in tumor cells correlates with enhanced expression and activity of MMPs, leading to enhanced matrix degradation and a release of cytokines and growth factors, thereby promoting metastasis." (PMID 35164076, 2022). "In other words, in different experimental systems, SOD2 overexpression can either stimulate tumor growth and metastasis or suppress them." (PMID 36552527, 2022). "Further, in vivo animal experiments should be further implemented to verify Pro’s action on OC tumor growth via modulating circ-ZFR/MiR-212-5p/SOD2 axis." (PMID 35543376, 2022). "Analyses of data in The Human Protein Atlas further revealed that both PSTK and SOD2 were expressed at high levels in HCC relative to other tumor types." (PMID 34983546, 2022). "As one of three isoforms of superoxide dismutase (SOD), SOD2 is known for its ability to act as both an oncogene and tumor suppressor." (PMID 33535682, 2021). "The data concerning the expression and activity of SOD, SOD1, and SOD2 in blood and tumor cells are ambiguous." (PMID 34832849, 2021). "Among anti-oxidant molecules, the expression of SOD2 was increased and was associated with the ALDH-positive tumor-initiating cell features." (PMID 34681918, 2021). "A multivariate analysis, including clinicopathological parameters such as age, anatomopathological tumor grade, type of treatment, and SOD2 expression, revealed that SOD2 expression was an independent prognostic factor." (PMID 34062984, 2021). "Oxidative stress was evaluated by detecting the expression of iNOS (a family of enzymes catalyzing the production of nitric oxide), 4HNE (one of several lipid peroxidation end-products), and SOD2 (mitochondrial superoxide scavenger) in the tumor." (PMID 33918787, 2021). "Enhancement of tumor-initiating cell features has been reported to accompany increased expression of SOD2, and as a result, strengthen the cells by superior ROS adjustment." (PMID 34681918, 2021). "Comparing frozen biopsy specimens of lung, colon, and prostate tissues, SOD2 was expressed in higher amounts during tumor progression when compared to controls." (PMID 34062984, 2021). "In particular, increased SOD2 activity was shown to facilitate cell migration and tumor invasiveness in other investigations." (PMID 34832849, 2021). "Our results suggested that Tf-D-HKC8 peptide-mediated interruption of HKDC1 suppressed tumor growth with overexpression of SOD2 and OGG1 completely and partly reversing this effect, respectively." (PMID 33423158, 2021).
tumor (continued). "Studies have demonstrated that SOD2 overexpression can enhance the invasion and metastasis of tumor cells by increasing the expression of matrix metalloproteinases (MMP) family members or activating Redox sensitive signaling pathways." (PMID 34093804, 2021). "TMZ resistance is conferred by the accumulation of superoxide dismutase 2 (SOD2), which regulates ROS levels and protects tumor cells against oxidative stress." (PMID 34646780, 2021). "Though this result remains far from a clinical application, our identification of SOD2 as a crucial molecule in the induction of drug resistance helps to understand the role of the protein and the specific cells in the tumor tissue." (PMID 34681918, 2021). "The box plot of SOD2 protein expression showed that the protein expression of the tumor tissue was higher than that of the normal tissue." (PMID 34721758, 2021). "Similar unexpected findings were found for SOD2 (manganese mitochondrial SOD, MnSOD), for which high levels were found in tumor tissues, particularly in stages II and III of malignancy versus stage I or precancerous stage." (PMID 34948180, 2021). "Of note, these changes were reported to be strictly related with the aerobic glycolysis in tumor cells as a consequence of SOD2-induced activation of AMPK, which further led glucose metabolism via glycolysis." (PMID 34948180, 2021). "Exposure of Cd to TM3 tumor LCs decreases SOD2 and GSH contents by targeting the Nrf2/ARE signaling pathway, thereby decreasing T production." (PMID 32528534, 2020). "Previous reports have shown that SOD2 levels appear to surge during metastatic progression in highly aggressive tumor cells." (PMID 32585852, 2020). "SOD2, as one of the most crucial enzymes against mitochondrial ROS, has also been found to act as a potential tumor suppressor gene in carcinogenesis." (PMID 31929112, 2020). "In order to target tumor cell mitochondria, applying biguanides to replacement therapy or drug repositioning should be proposed for patients with SOD2-abundant RCC for maintenance phase treatments after primary surgery debulking numbers of RCC cells." (PMID 33092599, 2020). "In PAH, the best described is hypermethylation of the gene encoding superoxide dismutase 2 (SOD2), an enzyme involved in H2O2 regulation which also acts as a tumour suppressor gene." (PMID 33256119, 2020). "Genome-wide RNA-seq studies on HCC tumor tissues and their adjacent nontumorous liver tissues revealed that hsa_circ_0004662, derived from SOD2 gene was significantly upregulated in HCC tumor tissues." (PMID 33234142, 2020). "Previous genome-wide RNA-seq studies on HCC tumor tissues and its adjacent normal liver tissues revealed that a circular RNA derived from SOD2 gene was highly expressed in tumor tissues compared to its adjacent normal liver tissues." (PMID 33234142, 2020). "Overall, these data suggested that SOD2 is critical for the malignant effects of radiotherapy and tumor progression through diverse endogenous factors." (PMID 30755594, 2019). "SOD1 has high overall expression in breast tissue, and its expression is further increased in tumor tissues, whereas SOD2 and SOD3 are expressed at approximately levels twofold lower than SOD1 levels." (PMID 29478325, 2019). "In one case with inconsistent scoring, obviously high SOD2 cell levels accounted for about 10% of tumor cells." (PMID 30700285, 2019). "The present findings demonstrated that SOD2 also mediates the invasion of un-irradiated cancer cells induced by upregulation of diverse oncogenic components, supporting the role of SOD2 in tumor progression." (PMID 30755594, 2019). "The overexpression of superoxide dismutase 2 (SOD2), an antioxidant enzyme, can also advance tumor growth and metastasis in OCCC." (PMID 31366141, 2019).
tumor (continued). "It has been suggested that the dichotomous function of SOD2 results from the context-dependent regulation of SOD2 during different stages of tumor development." (PMID 31870275, 2019). "Cases with stronger SOD2 staining of the tumor cells than normal ovarian stromal cells were categorized as high SOD2 cases." (PMID 30700285, 2019). "Early reports concerning SOD2 function in carcinogenesis showed a correlation between decreased SOD2 expression at the early initial stage of carcinogenesis and suggested a tumor suppressor role for the enzyme." (PMID 29478325, 2019). "SOD2 was identified as downregulated in tumors in early studies, and thus SOD2 was initially considered a tumor suppressor." (PMID 31658599, 2019). "In particular, SOD2 has been described as a tumor suppressor gene and its decreased expression level has been reported in a wide variety of diseases, including hematological malignancies." (PMID 30259659, 2018). "SELENOP, SELENBP1, and SOD2 had medium protein expression levels, in both the normal and the tumor cells." (PMID 30469315, 2018). "In most of the early documentations, SOD2 was implicated as a tumor suppressor; however, more recently, there is accruing evidence that of the oncogenic/tumor-promoting role of SOD2." (PMID 30103475, 2018). "We also observed lower levels of both SOD1 and SOD2 proteins in tumor tissue compared to adjacent healthy tissue." (PMID 29596499, 2018). "We analyzed total SOD activity as well as SOD1 and SOD2 protein levels in tumor and adjacent healthy breast tissue." (PMID 29596499, 2018). "We believe that the dichotomous regulation and role of SOD2 can explain its role as both a tumor suppressor in early tumorigenesis and as a tumor promoter during metastatic progression." (PMID 29099803, 2017). "Future studies examining the role of altered tumor metabolism and different tumor metastatic niches on epigenetic regulation should further shed light on the influence of context-dependent epigenetic regulation of SOD2." (PMID 29099803, 2017). "The experimental results showed that intratumoral injection of SOD2 overexpressing lentivirus can effectively inhibit tumor growth compared with other experimental treatments." (PMID 27999194, 2017). "We first measured the gene expression from tumor tissues, including SOD2, AHR and VEGF, for both mRNA and protein levels." (PMID 29212263, 2017). "In vitro experiments showed that radiotherapy combined with SOD2 overexpression can effectively inhibit the proliferation and growth of tumor cells and promote tumor cell apoptosis, while decreasing the apoptosis rate of normal cells after irradiation." (PMID 27999194, 2017). "SOD2 overexpression has “double effects,” namely, sensitizing tumor cells while protecting normal cells during radiation therapy." (PMID 27999194, 2017). "Since the discovery of direct regulation of SOD2 by NF-κB, it has been demonstrated that this stress response pathway is involved in anti-apoptosis, tumor metastasis and radiation resistance." (PMID 29099803, 2017). "To further investigate the mechanism of upregulation of SOD-2 in AFG1-induced lung tumor, we treated A549 cells and MΦ-THP-1 cells with AFG1, TNF-α and/or IL-6 to mimic the AFG1-induced tumor-associated inflammatory microenvironment in vitro." (PMID 28801561, 2017). "Radiotherapy combined with SOD2 overexpression in tumor xenografts can inhibit growth of tumor xenografts and increase the apoptosis rate of tumor cells." (PMID 27999194, 2017). "Second, the effects of SOD2 overexpression on tumor cells are different from those on normal cells in tumor radiotherapy." (PMID 27999194, 2017). "SOD2 regulation by stress response pathways, such as NF-κB, hence allows for transient SOD2 expression in response to changing tumor microenvironments." (PMID 29099803, 2017). "SOD2 overexpression in skin tissue adjacent to the tumor xenograft reduces the apoptosis rate of skin cells after irradiation." (PMID 27999194, 2017).
tumor (continued). "in vivo mice study showed that BA/CDM combination significantly suppressed AML tumor growth, and overexpression of SOD2 and a constitutive HIF1α (HIF1C) completely diminished this effect." (PMID 29212263, 2017). "Due to its cytoprotective function of scavenging harmful O2•− at the major cellular metabolic hub, SOD2 was traditionally considered a tumor suppressor." (PMID 29099803, 2017). "Examples of these and how different tumor types and stages of cancer can influence SOD2 regulation are provided." (PMID 29099803, 2017). "An additional important observation is the dichotomous role and regulation of SOD2 during tumor progression." (PMID 29099803, 2017). "Remarkably, the tumor-promoting effects of CAV1−/− fibroblasts were reverted by recombinant overexpression of superoxide dismutase 2 (SOD2), thus implying that oxidative stress is critical for facilitating Cav-1 loss-induced carcinogenesis." (PMID 28546853, 2017). "Studies have shown that SOD2 can act as a tumor suppressor, which inhibits tumor proliferation, invasion and metastasis, as well as promote apoptosis of tumor cells." (PMID 27999194, 2017). "Previous studies also showed that overexpression of SOD2 in tumor cells can enhance radiosensitivity of tumor cells rather than act as a protector." (PMID 27999194, 2017). "The state of cell growth was poor and more necrotic foci were found in tumor tissues of the SOD2 + R group compared with other treatment groups." (PMID 27999194, 2017). "Given that CDK4 is an important cell cycle regulator of cancer cells, this co-regulation of SOD2 requires further investigation in the context of tumor cells and their response to radiation and chemotherapy induced stress." (PMID 29099803, 2017). "Mitochondria are the likely source of intracellular ROS because expression of mitochondrial SOD2 can suppress tumor growth and invasion of scrib−/−RasV12 tumors." (PMID 28853394, 2017). "In vitro experiments revealed that radiation-induced SOD2 overexpression inhibited tumor cell proliferation (61.89% vs. 40.17%, P < 0.01) and decreased apoptosis among normal cells (14.8% vs. 9.6%, P = 0.02) as compared to untransfected cells." (PMID 27999194, 2017). "The regulation of SOD2 by stress response transcription pathways such as Nrf2 is one example of how histological tumor subtypes can display differences in SOD2 expression." (PMID 29099803, 2017). "SOD2 has both tumor suppressive and promoting functions, which are primarily related to its role as a mitochondrial superoxide scavenger and H2O2 regulator." (PMID 29099803, 2017). "To solve the problem of increased tumor radiosensitivity aggravating normal-tissue damage, we attempted to construct the SOD2 overexpressing lentivirus vector that is driven by a radiation-inducible chimeric promoter." (PMID 27999194, 2017). "Radiation-induced overexpression of SOD2 can increase the efficacy of tumor radiotherapy and improve the quality of life of cancer patients." (PMID 27999194, 2017). "The results demonstrated that the tumor inhibitory effect of the SOD2 + R group was the most effective among all treatment groups." (PMID 27999194, 2017). "The expression of SOD2 in tumor cells was significantly increased in the SOD2 + R group compared with other groups." (PMID 27999194, 2017). "SOD2 expression similarly provides a protective advantage to tumor cell mitochondria through SOD2’s canonical role as a O2•− scavenger." (PMID 29099803, 2017). "These clinical data suggest that SOD2 has a tumor suppressive function in HCC tumorigenesis and progression and that SOD2 protein expression is a potentially useful prognostic biomarker in this patient population." (PMID 27221200, 2016). "In human breast cancer cell (MCF-7) and rat glioma cells, overexpression of SOD2 also inhibits the malignant phenotype of several human tumor cell lines, possibly through inhibition of AP-1 and NF-κB." (PMID 27023612, 2016).
tumor (continued). "Reduced SOD2 expression in HCCs is correlated with older age, larger tumor size, multiple tumor nodules and tumor emboli, and cancer recurrence." (PMID 27221200, 2016). "The drug combination increased the levels of reactive oxygen species in cells, and over-expression of TRX or SOD2 prevented drug combination tumor cell killing." (PMID 26981780, 2016). "Since anoikis resistance is essential for tumor metastasis the anti-anoikis activity of SOD2 implicates this enzyme in the metastatic process." (PMID 25745358, 2015). "The influences of OA on the protein expressions of HIF1α, SIRT3, and SOD2 in tumor tissue of the nude mice inoculated with MCF-7 cells were consistent with that inoculated with MDA-MB-231 cells." (PMID 25855962, 2015). "Tumor cells must adapt in order to evade this fate and therefore commonly over-express antioxidant enzymes, such as superoxide dismutase 2 (MnSOD, SOD2) and peroxiredoxin 3 (PRX3), which permits escape from oncogene-induced senescence." (PMID 25462069, 2014). "Considering the roles of SOD2 in cellular differentiation, survival, the nervous system, and in tumour pathogenesis and progression, we have assessed the influence of the TrkAIII oncogene upon SOD2 expression, activity and function in human SH-SY5Y NB cells." (PMID 24736663, 2014). "In contrast, other studies have demonstrated that expression of Sod2 maintains the metabolic activity of cancer cells when they are detached from the extracellular matrix and that it increases tumor promotional nuclear factor (NFκB) signaling." (PMID 25358638, 2014). "While the phenotypic effects of diminished and/or overexpressed SOD2 have been reported for various tumour cell lines, the explanation for reduced expression has only recently emerged." (PMID 17895890, 2007). "While homozygous sod2 knockout mice die within weeks, heterozygous +/− mice have accelerated tumour development, particularly lymphomas." (PMID 17895890, 2007). "The cytoprotective and antioxidant genes, such as GPX1, CAT, and SOD2, are some examples of NRF2-regulated genes that could be implicated in tumor progression, metastasis, and resistance to chemotherapy." (PMID 40565143, 2025). "Additionally, deacetylation of SOD2 has been linked to cancer stem cell formation via activation of HIF-2α, contributing to tumor aggressiveness and poor clinical outcomes." (PMID 41154474, 2025). "Furthermore, in contrast to cell growth in monolayer, we assessed the effect of SOD2 in anchorage-independent growth models, which better mimic the pathophysiological tumor condition." (PMID 40430023, 2025). "Additionally, during pre-invasive stages, tumor cells enhance local ROS clearance by upregulating antioxidant enzymes like SOD2 and GPX4, which aid in evading immune surveillance and enhance metastatic potential." (PMID 40563367, 2025). "Elevated SOD2 also suppresses recurrent tumor growth by quiescent PCa cells and prolongs survival." (PMID 40520023, 2025). "Similarly, the antioxidant enzyme superoxide dismutase 2 (SOD2) demonstrates context-dependent functions, acting as both protective and tumor-supportive depending on redox status and treatment exposure." (PMID 41018144, 2025). "Besides, genetic overexpression of SOD2 demonstrated more sustained tumor suppression than PTE, likely due to the inherent limitations of small-molecule therapeutics." (PMID 40520023, 2025). "The dichotomous role of SOD2 in cancer may be attributed to the diverse roles of ROS in oncogenic pathways, which vary according to their source and the stage of tumor development." (PMID 41154474, 2025).